RELCH (RAB11 binding and LisH domain, coiled-coil and HEAT repeat containing)
Description:
Regulates intracellular cholesterol distribution from recycling endosomes to the trans-Golgi network through interactions with RAB11 and OSBP. Functions in membrane tethering and promotes OSBP-mediated cholesterol transfer between RAB11-bound recycling endosomes and OSBP-bound Golgi-like membranes.
Synonyms: KIAA1468; HsT885; HsT3308; FLJ33841
Tractability: PROTAC: ubiquitination databases record sites on it.
Gene: Protein-coding gene on chromosome 18 (62,187,255 to 62,310,249, forward strand). Ensembl gene ENSG00000134444.
Subcellular location: Recycling endosome; Golgi apparatus, trans-Golgi network
Gene Ontology:
Biological process: intracellular cholesterol transport
Cellular component: recycling endosome; trans-Golgi network; Golgi apparatus
Genetic constraint (gnomAD): Loss-of-function variants: 13 observed, 55.87 expected, observed/expected ratio (o/e) 0.23, 90% interval 0.15 to 0.37. The upper end of that interval is the gene's LOEUF score, 0.37, which puts it in group 1 of 6, group 1 being the genes least tolerant of losing a copy. Missense variants: 651 observed, 829.37 expected, observed/expected ratio (o/e) 0.78, 90% interval 0.74 to 0.84. Synonymous variants: 291 observed, 314.17 expected, observed/expected ratio (o/e) 0.93, 90% interval 0.84 to 1.02.
Homologues: Orthologues: chimpanzee RELCH (99% identical), macaque RELCH (99% identical), rabbit RELCH (96% identical), pig RELCH (96% identical), dog RELCH (96% identical), mouse Relch (94% identical), rat Relch (94% identical), guinea pig RELCH (82% identical), tropical clawed frog relch (79% identical), zebrafish relch (74% identical).
Diseases named in the same sentence as RELCH in open-access papers:
RELCH is named in the same sentence as 3 diseases in open-access papers, as found by Europe PMC text mining. Sharing a sentence is not in itself a finding about the gene and the disease. The quoted sentences say what the papers report.
epilepsy (1 paper, 2025). A brain disorder characterized by episodes of abnormally increased neuronal discharge resulting in transient episodes of sensory or motor neurological dysfunction, or psychic dysfunction. "The VerteBrain dataset uncovers candidate disease mechanisms, including roles for ARHGEF1 in short stature syndromes, synaptic vesicle trafficking complexes in epilepsy, and RELCH in congenital deafness." (PMID 40501792, 2025).
RELCH also shares sentences with these, for which no sentence is quoted: asthma (1 paper); tumour (1).